GPC3 (glypican 3)
Diseases named in the same sentence as GPC3 in open-access papers (continued):
Sharing a sentence is not in itself a finding about the gene and the disease.
hepatocellular carcinoma (continued). "Glypican-3, a member of the glypican family of heparan sulfate proteoglycans, is highly and specifically expressed in hepatocellular carcinoma (HCC)." (PMID 31100975, 2019). "Contrarily, GPC3 is specifically expressed in hepatocellular carcinoma (HCC), ovarian clear cell carcinoma, melanoma, squamous cell carcinoma of the lung, hepatoblastoma, nephroblastoma (Wilms tumor), yolk sac tumor, and some pediatric cancers." (PMID 31024850, 2019). "In this context, our findings would not be contradictory to studies that have described an overexpression of GPC3 in the serum of patients with hepatocellular carcinoma, assuming that the soluble form of GPC3 was measured." (PMID 31100935, 2019). "It was recently reported that GPC3 was overexpressed in the serum samples of hepatocellular carcinoma (HCC) patients compared with that in patients with liver cirrhosis or chronic hepatitis or healthy donors." (PMID 31160489, 2019). "I-124 codrituzumab (aka GC33), an antibody directed at Glypican 3, was evaluated in patients with hepatocellular carcinoma (HCC)." (PMID 29508107, 2018). "At the same time, the GPC3 gene inhibits hepatocellular carcinoma cells, and plays an important role in immunity, while sterile α and TIR motif containing one (SARM1) genes are also related to immunity, and are responsible for regulating neuronal inflammation." (PMID 29187421, 2018). "Recently, it was shown that GPC3 is highly expressed in the majority of hepatocellular carcinomas (HCCs)." (PMID 29508107, 2018). "Glypican-3, a member of the glypican family of heparan sulfate proteoglycans, is also involved in the progression of hepatocellular carcinoma (HCC)." (PMID 30463366, 2018). "GPC-3 and hepatocyte are both specific markers for hepatocellular carcinoma, which were also positive in the tumor cells in the current case." (PMID 29351804, 2018). "Glypican-3 (GPC3) is a promising new marker for hepatocellular carcinoma, but the reported values for serum GPC3 differ markedly between currently available kits." (PMID 28852111, 2017). "The high positive rate of GPC3 in hepatocellular carcinoma indicates the specificity of GPC3 in hepatocyte-origin carcinogenesis." (PMID 28510121, 2017). "One of these is a phase II trial of codrituzumab (humanized monoclonal antibody against GPC3) in previously treated patients with advanced hepatocellular carcinoma." (PMID 28077782, 2017). "The mean level of GPC3 in serum was higher (>8.5 fold, P < 0.001) in hepatocellular carcinoma patients compared to healthy and other liver disease individuals." (PMID 28852111, 2017). "GPC3 was considered as important as alpha-fetoprotein in a fast and effective cell sorting strategy to specifically identify hepatocellular carcinoma circulating cells." (PMID 28510121, 2017). "Glypican-3 was recently suggested to be a critical part of molecular mechanisms by which the proliferation and invasion of hepatocellular carcinoma are regulated and controlled." (PMID 28510121, 2017). "The green part showed a grade III hepatocellular carcinoma with an immunoreaction to Hep Par 1, glypican 3 and α-fetoprotein, whereas the white part exhibited a small cell carcinoma, as evidenced by expressions of chromogranin A and synaptophysin." (PMID 28834900, 2017). "GPC3 has been recently reported and suggested as a novel potential oncofetal biomarker for diagnosis in a number of cancer diseases such as hepatocellular carcinoma." (PMID 28510121, 2017). "An early group has suggested that miR-219 was significantly downregulated in hepatocellular carcinoma, also exerted tumor-suppressive effects in hepatic carcinogenesis via inhibiting transcription and translation of glypican-3." (PMID 28915609, 2017). "Glypican-3 (GPC3) is a cell surface-bound proteoglycan which has been identified as a potential biomarker candidate in hepatocellular carcinoma, lung carcinoma, severe pneumonia, and acute respiratory distress syndrome (ARDS)." (PMID 28510121, 2017).
hepatocellular carcinoma (continued). "This group is studying antibodies that target glypican-3 (GPC3), a cell-surface heparan sulfate proteoglycan highly expressed in hepatocellular carcinoma (HCC)." (PMID 28574434, 2017). "A clinical trial of codrituzumab, a humanized monoclonal antibody against GPC3, was recently performed in a randomized phase II trial in advanced hepatocellular carcinoma patients who had failed prior systemic therapy." (PMID 28510121, 2017). "The combination of GPC3 and cytokeratin 19 expression in the cancer tissue was suggested as an independent prognostic indicator in patients with hepatocellular carcinoma." (PMID 28510121, 2017). "Cytokeratin-19 (CK19) and glypican-3 (GPC3) are both routine pathological diagnosis biomarkers for the primary carcinoma of the liver." (PMID 28276470, 2017). "The positive rate of hepatocellular carcinoma circulating cells was above 90% in combination of GPC3 with alpha-fetoprotein." (PMID 28510121, 2017). "and Ho, M. Humanization of high-affinity antibodies targeting glypican-3 in hepatocellular carcinoma." (PMID 27667400, 2016). "In this regard, GPC3 overexpression has been shown in Wilms' tumor, hepatocellular carcinoma (HCC), yolk sac tumor and clear cell ovarian carcinoma." (PMID 27507057, 2016). "Among these targets, GPC3 is very attractive for therapeutic design because it is uniquely overexpressed in hepatocellular carcinoma." (PMID 27669301, 2016). "In contrast, GPC3 silencing leads to a decrease in the migratory capacity of hepatocellular carcinoma cell lines." (PMID 27507057, 2016). "In other tumor types, such as hepatocellular carcinoma, where GPC3 functions as an oncogene, GPC3-mediated oncogenesis involves the activation of Wnt or Insulin-like growth factor signaling." (PMID 27259271, 2016). "As a corollary, GPC3 is a recognized prognostic/predictive factor and therapeutic target in hepatocellular carcinoma." (PMID 25935541, 2015). "Some studies have shown that GPC3 plays an important role in cell growth and differentiation, such as in the case of hepatocellular carcinoma." (PMID 25168166, 2014). "Enhanced glypican-3 expression differentiates the majority of hepatocellular carcinomas from benign hepatic disorders." (PMID 25168166, 2014). "Relationship between glypican-3 (GPC3) expression and clinical features of patients with hepatocellular carcinoma." (PMID 24498024, 2014). "In this present study, a specific short hairpin RNA (shRNA) was screened and applied to silence GPC-3 gene transcription for observing its effect on proliferation of human hepatoma cells." (PMID 23192642, 2013). "In hepatocellular carcinoma, miR-219-5p was found to be downregulated and was found to target glypican-3 (GPC3) which play role in cell division." (PMID 23690991, 2013). "There is also a very high occurrence of GPC3 over-expression in hepatocellular carcinoma where it is considered as a serum marker and potential therapeutic target." (PMID 24244720, 2013). "Glypican-3 (GPC-3) is located at Xq26.1 area on chromosome and promotes hepatoma cell growth by stimulating canonical Wnt signaling." (PMID 23192642, 2013). "Glypican-3 (GPC3) is a heparan-sulfate proteoglycan frequently expressed on the cell membrane of malignant hepatocytes in hepatocellular carcinoma." (PMID 22564378, 2012). "An anti-glypican-3 murine IgG antibody that induces antibody-dependent cytotoxicity has been shown to have anti-tumor effect in a xenograft animal model of hepatocellular carcinoma but required partial humanization before entering human clinical trials." (PMID 22564378, 2012). "GPC3 in particular has been shown to increase Wnt signaling in hepatocellular carcinoma via interaction between Wnt and GPC3 core protein." (PMID 20868507, 2010). "Because GPC3 is over expressed in human hepatocellular carcinoma, this marker is used for hepatocellular tumours in human medicine as a marker for malignant change." (PMID 20167095, 2010).
hepatocellular carcinoma (continued). "On the other hand, GPC3 has been shown to be overexpressed in hepatocellular carcinomas and to be associated with advanced stages as well as with the invasive potential of this cancer." (PMID 15083193, 2004). "GPC3 has been shown to be overexpressed preferentially in female as compared to male hepatocellular carcinomas (females, 95% and males, 67%)." (PMID 15083193, 2004). "Similarly, GPC3-targeted allogeneic CAR-T cells based on a single-domain antibody showed robust activity against hepatocellular carcinoma cells in vitro and in vivo." (PMID 42094429, 2026). "Similarly, in hepatocellular carcinoma models, GPC3-directed CARs combined with AFP-specific TCRs address intratumor heterogeneity." (PMID 41348261, 2025). "GPC3, known as a tumor marker in certain cancers (e.g., hepatocellular carcinoma), may serve a similar role in gastric cancer, suggesting that high expression in specific cell types could aid in disease prognosis." (PMID 40092689, 2025). "Finally, glypican-3-binding peptides (GPC3) have been identified as selective targeting agents for hepatocellular carcinoma (HCC)." (PMID 40286158, 2025). "The lncRNA GPC3 antisense transcript 1 (GPC3-AS1) is responsible for the upregulation of GPC3 in hepatocellular carcinoma cells, raising the question whether this mechanism could be leveraged to stimulate the expression of GPC3 in BC cells." (PMID 40443562, 2025). "A phase 1 clinical trial (NCT03198546) evaluating CAR-T cells with constitutive expression of IL-7 and CCL19 in six patients with progressive hepatocellular carcinoma, pancreatic carcinoma, and ovarian carcinoma expressing either GPC3 or MSLN showed promising results." (PMID 41154636, 2025). "Additionally, iron oxide nanoparticles (Fe3O4 NPs) functionalized with glypican-3 ligand peptides (GPC3) were developed for ultrasound imaging and cancer therapy, particularly in hepatocellular carcinoma." (PMID 40286158, 2025). "The sensitive detection of GPC3 facilitates the early detection of hepatocellular carcinoma (HCC)." (PMID 40710102, 2025). "Although CAR-T therapy has demonstrated significant efficacy in clinical trials for specific solid tumors (such as CEA-targeted colorectal cancer and GPC3-targeted hepatocellular carcinoma), its efficacy is inherently limited by the biological background of the tumor." (PMID 40969260, 2025). "Several therapeutic monoclonal antibodies targeting GPC3 have been developed, such as GC33, which has demonstrated antibody-dependent cell-mediated cytotoxicity against GPC3-positive hepatocellular carcinoma (HCC) cell lines and inhibition of tumor growth in mouse models of HCC." (PMID 38727261, 2024). "However, GPC3 CAR-T cell therapy for hepatocellular carcinoma remains in its early stages, with its methods and effects yet to meet clinical needs." (PMID 39136031, 2024). "The reported 44% rate of GPC3 expression in pancreatic cancer raises the important possibility that targeted immunotherapies currently in development for hepatocellular carcinoma may also prove useful for GPC3-expressing pancreatic cancers." (PMID 39598037, 2024). "GPC3 immunohistochemistry has become recognized as a clinically helpful diagnostic marker for pathologists to distinguish hepatocellular carcinoma from benign hepatocellular tumors and from many non-hepatocellular neoplasms." (PMID 39598037, 2024). "This suggests GPC3’s potential as a prognostic marker for hepatocellular carcinoma." (PMID 39136031, 2024). "Notably, GPC3 is highly expressed in hepatocellular carcinoma and squamous non-small cell lung cancer but is expressed at low levels in other cancers." (PMID 39136031, 2024). "In addition, Lin28 is also overexpressed in hepatocellular carcinoma, and regulating Lin28B enhance the anti-tumor activity of GPC3 CAR-T cells, enabling GPC3 CAR-T cells to better treat hepatocellular carcinoma." (PMID 39136031, 2024). "This greatly enhances the treatment of hepatocellular carcinoma by GPC3 CAR-T cells." (PMID 39136031, 2024).
hepatocellular carcinoma (continued). "We used immunohistochemistry to detect the expression frequency of glypican-3 (GPC3) in OCCC, which is a well-recognized diagnostic marker of the hepatocellular carcinoma and highly heterogeneous in other cancers such as OCCC, so as to provide a clear clinical basis for future drug development." (PMID 38824600, 2024). "GPC3 can promote the proliferation and tumour formation of hepatocellular carcinoma cells." (PMID 37036308, 2023). "This conjugate could use for subcutaneous hepatocellular carcinoma imaging in vivo, indicating that it might be a potential agent in glypican-3 positive tumor imaging for diagnosing hepatocellular carcinoma." (PMID 36910146, 2023). "This aptamer targets Glypican-3 described as a biomarker for hepatocellular carcinoma." (PMID 34844535, 2023). "Glypican-3 (GPC-3) is a cell surface-bound oncofetal proteoglycan which has been identified as a potential prognostic factor and immunotherapeutic target in hepatocellular carcinoma (HCC), lung carcinoma, severe pneumonia, and acute respiratory distress syndrome (ARDS)." (PMID 37446098, 2023). "Subgroup 0 included hepatoma cells specifically expressing GPC3, CD24 and MDK." (PMID 37305578, 2023). "In addition, it was reported that GPC3-GC was partially similar to hepatocellular carcinoma histologically, and functionally expressed albumin mRNA." (PMID 35050429, 2022). "GAL and siGPC-3 can induce targeted silencing of GPC-3 gene in hepatoma cells." (PMID 35497343, 2022). "Finally, siRNA-mediated transient GPC3 silencing inhibits the invasion and migration of hepatocellular carcinoma cells." (PMID 35965506, 2022). "Hepatocellular carcinoma can be diagnosed early via the GPC3 and GS status as detected by RNAscope." (PMID 35027056, 2022). "Given that GPC3 is a well-known oncogene in hepatocellular carcinoma, we concluded that miR-4510 might act as a tumor suppressor in Glypican3-expressing gastric cancer." (PMID 35050429, 2022). "Also reported in the literature, GPC3 has been proved to have high specificity in the diagnosis of hepatocellular carcinoma and can be used as a marker to distinguish hepatocellular carcinoma from other liver tumors." (PMID 35345673, 2022). "Hepatocellular carcinoma (HCC) is the most studied cancer in which GPC3 is highly expressed." (PMID 36142190, 2022). "In addition, compared with IHC, RNAscope improved both the specificity and sensitivity for GPC3 and GS by 20–30% in hepatocellular carcinoma." (PMID 35027056, 2022). "Moreover, there is the role of GPC-3 for being a marker and a therapeutic target of hepatocellular carcinoma." (PMID 35204421, 2022). "Multiple ITs have been designed against GPC3 of hepatocellular cancer cells." (PMID 34822533, 2021). "In addition, a humanized anti-human GPC3 antibody, GC33, was tested in clinical trials to examine the pharmacokinetics, dosage and duration of treatment, safety and tolerability, and antitumor activity in GPC3 high expression hepatoma cells." (PMID 34306031, 2021). "Glypican-3, a cell-surface glycoprotein in which heparan sulfate glycosaminoglycan chains are covalently linked to a protein core, is overexpressed in hepatocellular carcinoma (HCC) tissues but not in the healthy adult liver." (PMID 33466827, 2021). "The immunohistochemical markers of hepatocellular carcinoma include those of hepatocellular differentiation—such as hepatocyte paraffin 1 and arginase-1—and those of malignant hepatocytes—such as glypican-3, heat shock protein 70, and glutamine synthetase (GS)." (PMID 34071338, 2021). "Later, Mu and colleagues (2014) reported that GPC3 could be found both at the plasma membrane and in the cytoplasm of hepatocellular carcinoma cells." (PMID 33947326, 2021). "Besides (OC) group, Glypican-3 (Gpc3) was additionally stained as a common overexpressed marker for hepatocellular carcinoma (HCC) patients (Patient 4 as representative)." (PMID 34641562, 2021).
hepatocellular carcinoma (continued). "Furthermore, anti-GPC3 scFv-modified exosomes effectively delivered miR-26a to GPC3-positive hepatocellular carcinoma cells, thereby inhibiting cell proliferation and migration by regulating the expression of downstream target genes of miR-26a." (PMID 34552961, 2021). "Similarly, increased expression of p62 and glypican-3 has observed in hepatoma Huh-7.5 cells, indicating impaired autophagic flux, and activation of functional autophagy in Huh-7.5 cells efficiently cleared p62 and glypican-3 expression." (PMID 33976943, 2021). "Furthermore, we developed a model combining age, gender, PIVKA-II, GPC-3 and adiponectin that showed an excellent performance for the identification of patients with hepatocellular carcinoma." (PMID 34064999, 2021). "Indeed, individual glypicans have been identified as prognostic factors in oesophageal squamous cell carcinoma (GPC1), hepatocellular carcinoma (GPC3) and ovarian cancer (GPC6)." (PMID 33742285, 2021). "Glypican 3 (GPC3) is a protein that regulates the proliferation of hepatocellular carcinoma cells." (PMID 34830312, 2021). "Antibody targeting oncofetal protein glypican-3 (high expression on hepatocellular carcinoma)." (PMID 32153582, 2020). "GPC3 was shown to be a valid tumor marker of hepatocellular carcinoma, which can be used for early detection of patients with hepatocellular carcinoma by blood screening.Hence, further investigations are needed to evaluate the association between GPC3 expression and its serum level." (PMID 32582830, 2020). "Therefore, in this study, GPC-3 is selected as a promising target for the identification of novel potent inhibitors against hepatocellular carcinoma (HCC)." (PMID 33126630, 2020). "Like free hGC33, nanodrug surface-modified hGC33 inhibited the proliferation of hepatoma cells not only by blocking Wnt-induced signal transduction in HepG2 and Huh-7 cells of expressing GPC3, but also by inhibiting Wnt3a-induced β-catenin and YAP signal transduction." (PMID 33242103, 2020). "GPC-3 CAR-T cells eliminated GPC-3 positive tumors in murine model of hepatocellular carcinoma." (PMID 32010611, 2019). "For example, GPC3 promotes hepatocellular carcinoma growth by activating WNT signaling." (PMID 30197623, 2018). "In contrast, GPC3 is upregulated in hepatocellular carcinoma, germ cell tumor, and lung squamous cell carcinoma, suggesting that GPC3 may also behave as an oncofetal protein." (PMID 30027065, 2018). "However, contrary to this, soluble GPC3 has been shown to block hepatocellular carcinoma growth by blocking WNT signaling and MAP kinase and AKT pathways." (PMID 30197623, 2018). "It is questioned whether the GPC3/Wnt β-catenin signal pathway is miR-133b/Sirt1-specific regulation or is the hepatocellular carcinoma cell-specific and/or dominated mechanism." (PMID 28510121, 2017). "Therefore, GPC3 was proposed as a useful tumor marker for cancer-diagnosis for patients with hepatocellular carcinoma." (PMID 28510121, 2017). "Glypican-3 could be considered as a clinically useful biomarker in hepatocellular carcinoma, lung carcinoma, and ARDS, but further research is needed to confirm and expand on these findings." (PMID 28510121, 2017). "Glypican-3 (GPC3) is overexpressed in hepatocellular carcinoma (HCC)." (PMID 27419635, 2017). "In addition, Gpc3, an ortholog of Gpc5, is reportedly involved in canonical Wnt signaling in hepatocellular carcinoma cells." (PMID 29215008, 2017). "In these cases the differential diagnosis requires the use of other markers such as S-100 and other tumour specific proteins according to the presumed origin (e.g PSA for prostatic carcinoma, glypican 3 for hepatocellular carcinoma, PAX8 for renal carcinoma and CDX-2 for colorectal carcinoma)." (PMID 26888362, 2016). "In addition, an established oncogene of hepatocellular carcinoma, GPC3, was included in these target genes, and showed a tumor-specific overexpression pattern." (PMID 27137948, 2016).